RPLP1 (ribosomal protein lateral stalk subunit P1)
Description:
Plays an important role in the elongation step of protein synthesis.
Synonyms: LP1; P1; RPP1
Tractability: Small molecule: an approved drug acts on it; a high-quality ligand is known. PROTAC: UniProt records ubiquitination sites on it; ubiquitination databases record sites on it; its protein half-life has been measured; a small molecule that binds it is known. Other modalities: a drug acting on it is in phase 2 or 3 trials.
Target class: Other cytosolic protein
Gene: Protein-coding gene on chromosome 15 (69,452,809 to 69,456,205, forward strand). Ensembl gene ENSG00000137818.
Subcellular location (Human Protein Atlas): Cytosol; Endoplasmic reticulum
Pathways (Reactome):
Metabolism of proteins: Eukaryotic Translation Termination; Formation of a pool of free 40S subunits; GTP hydrolysis and joining of the 60S ribosomal subunit; L13a-mediated translational silencing of Ceruloplasmin expression; PELO:HBS1L and ABCE1 dissociate a ribosome on a non-stop mRNA; Peptide chain elongation; Ribosome Quality Control (RQC) complex extracts and degrades nascent peptide; SRP-dependent cotranslational protein targeting to membrane; ZNF598 and the Ribosome-associated Quality Trigger (RQT) complex dissociate a ribosome stalled on a no-go mRNA
Metabolism of RNA: Major pathway of rRNA processing in the nucleolus and cytosol; Nonsense Mediated Decay (NMD) enhanced by the Exon Junction Complex (EJC); Nonsense Mediated Decay (NMD) independent of the Exon Junction Complex (EJC)
Cellular responses to stimuli: Response of EIF2AK4 (GCN2) to amino acid deficiency
Developmental Biology: Regulation of expression of SLITs and ROBOs
Disease: Viral mRNA Translation
Metabolism: Selenocysteine synthesis
Gene Ontology:
Molecular function: protein binding; structural constituent of ribosome; protein kinase activator activity; ribonucleoprotein complex binding
Biological process: cytoplasmic translation; negative regulation of myoblast fusion; spermatogenesis; striated muscle contraction; translation; translational elongation
Cellular component: cytosol; cytosolic large ribosomal subunit; cytosolic ribosome; endoplasmic reticulum; focal adhesion; cytoplasm; ribosome
Genetic constraint (gnomAD): Loss-of-function variants: 4 observed, 9.13 expected, observed/expected ratio (o/e) 0.44, 90% interval 0.22 to 1. That is too few expected variants to judge how well the gene tolerates losing a copy. Missense variants: 133 observed, 117.15 expected, observed/expected ratio (o/e) 1.14, 90% interval 0.99 to 1.31. Synonymous variants: 51 observed, 47.54 expected, observed/expected ratio (o/e) 1.07, 90% interval 0.86 to 1.36.
Homologues: Orthologues: dog RPLP1 (100% identical), macaque RPLP1 (100% identical), mouse Rplp1 (97% identical), rabbit RPLP1 (97% identical), guinea pig RPLP1 (96% identical), mouse Rplp1rt (89% identical), zebrafish rplp1 (83% identical), tropical clawed frog rplp1 (81% identical), Caenorhabditis elegans rla-1 (61% identical), Drosophila melanogaster RpLP1 (61% identical). Paralogues in human: RPLP0 (48% identical), RPLP2 (37% identical).
Diseases named in the same sentence as RPLP1 in open-access papers:
RPLP1 is named in the same sentence as 44 diseases in open-access papers, as found by Europe PMC text mining. Sharing a sentence is not in itself a finding about the gene and the disease. The quoted sentences say what the papers report.
breast carcinoma (8 papers, 2016 to 2026). "Overexpression of RPLP1 in MDA-MB-231 breast cancer cells was associated with significant increases in protein expression for N-cadherin, snail and vimentin." (PMID 36769010, 2023). "Since we found that RPLP1 was associated with histologic grades, we further investigated the role of RPLP1 in breast cancer prognosis." (PMID 30386179, 2018). "As breast cancer represents another important feminine cancer, that is associated with hormone changes, we elected to investigate the role of RPLP1 in breast tumors." (PMID 30386179, 2018). "We identified the BRCA1 pseudogene (BRCA1P1), a fusion pseudogene derived from the BRCA1 tumor suppressor and RPLP1 ribosomal protein genes, as an immunoregulatory RNA in breast cancer." (PMID 42081726, 2026). "When CtE values from ERα+ breast cancer cell lines were supplied, RPLP1 was again ranked top RG candidate with the least variability in expression, according to RefFinder, BestKeepeer and the comparative ΔCt method." (PMID 39838295, 2025). "For the TNBC group, RPL30 was placed first by all programs, apart from GeNorm which recommended RPL27 and RPLP1, the same as for all four breast cancer cell lines." (PMID 39838295, 2025). "Although elevated expression was also observed in breast cancer PBMCs, RPLP1 may still have potential as a minimally invasive and cost-effective screening biomarker for melanoma, given its high sensitivity in this study cohort." (PMID 42302079, 2026). "Unsurprisingly, RPLP1 has emerged as a novel factor in the pathophysiology of these diseases as well as other cancers outside of the female reproductive tract, which include liver and breast cancer." (PMID 36769010, 2023). "RPLP1, an acidic ribosomal protein that recruits transcription factors in protein synthesis, has also been demonstrated to be related to primary cell transformation and breast cancer progression." (PMID 32051425, 2020). "Our results also indicated that RPLP1 may be a novel target to prevent or reduce breast cancer metastasis and could be the basis for future anti-cancer therapies, especially for difficult to treat TNBC." (PMID 30386179, 2018). "Following identification of optimal RGs, we aimed to evaluate combined use of RPLP1 and RPL27 for normalisation of gene transcription in a panel of normoxic and hypoxic breast cancer cell lines." (PMID 39838295, 2025). "For the study of hypoxia-mediated alterations in gene expression between MCF-7, T-47D, MDA-MB-231 and MDA-MB-468 breast cancer cell lines, GeNorm recommended the combined use of RPL27 and RPLP1." (PMID 39838295, 2025). "Our findings identify RPLP1, or RPLP1 in combination with RPL27, as optimal RGs for analysis of hypoxia-mediated gene transcription in MCF-7, T-47D, MDA-MB-231 and MDA-MB-468 breast cancer cell lines." (PMID 39838295, 2025). "RPLP1 can indeed lead to the accumulation of reactive oxygen, which activates the MAPK1/ERK2 signaling pathway and enhances the growth of breast cancer cells." (PMID 36984424, 2023). "Our identification of RPLP1 and RPL27 as robust RGs in this panel of hypoxic Luminal A and TNBC cell lines provides a valuable resource for future studies investigating important transcriptional changes occurring during breast cancer progression." (PMID 39838295, 2025). "Thus, combination of RPLP1 and RPL27 as RGs is suitable for normalising gene expression in this panel of normoxic and hypoxic breast cancer cell lines." (PMID 39838295, 2025). "However, the expression patterns of RPLP1 in breast cancer tissues, especially in TNBC, have not been thoroughly explored." (PMID 30386179, 2018).
embryonal tumors (3 papers, 2016 to 2024). "In embryonal tumors, the topmost DE genes included many ribosome-associated genes like RPS2, RPLP1, and RPL13A as well as histone H3.3 related genes like H3F3A and H3F3B." (PMID 36865335, 2023).
autoimmune disease (2 papers, 2023 to 2024). A disorder resulting from loss of function or tissue destruction of an organ or multiple organs, arising from humoral or cellular immune responses of the individual to their own tissue constituents. "Implicated in diseases like autoimmune disorders and cancer, they potentially contribute to tumorigenesis and metastasis, particularly RPLP1, which is associated with cell cycle regulation and malignant transformation." (PMID 39201300, 2024). "The ribosomal stalk, consisting of acidic ribosomal proteins RPLP0, RPLP1, and RPLP2, played an essential role in promoting translation subsets of cellular mRNAs, and closely linked to several pathological conditions, including autoimmune diseases and human malignancies." (PMID 37980521, 2023).
cancers of the ovary (2 papers, 2018 to 2023). "We recently reported over-expression of the 60S acidic ribosomal protein P1 (RPLP1) in endometrial epithelial cells from women with endometriosis, while Artero-Castro and colleagues reported over-expression of the RPLP protein family in cancers of the ovary and endometrium." (PMID 36769010, 2023).
cervical cancer (2 papers, 2020 to 2021). A primary or metastatic malignant neoplasm involving the cervix. "In conclusion, we verified that CNN3 acts as an oncogene to promote the viability and motility of cervical cancer cells in vitro and accelerate the growth and metastasis of xenografted tumours in vivo, by affecting RPLP1 expression." (PMID 32051425, 2020). "In contrast, CNN3 protein expression remained unchanged when RPLP1 expression was modulated, suggesting that RPLP1 is a candidate downstream gene in cervical cancer cells." (PMID 32051425, 2020). "Furthermore, we observed the effect of enforcedly changing RPLP1 expression on cellular proliferation, migration, and invasion in cervical cancer cells and found that the oncogenic function of RPLP1 is similar to that of CNN3." (PMID 32051425, 2020). "CNN3 affected RPLP1 mRNA expression in cervical cancer cells." (PMID 32051425, 2020). "CCK8, colony formation, and transwell assays showed that cellular proliferation, migration and invasion were enhanced in cervical cancer cells with RPLP1 overexpression, and, in contrast, were inhibited in cells with RPLP1 knockdown compared to cells without any gene modulation." (PMID 32051425, 2020). "In xenografted cervical cancer cells, CNN3 acted as an oncogene, promoting cell viability and motility in vitro by altering the expression of ribosomal protein lateral stalk subunit P1." (PMID 34305633, 2021). "Further, we identified ribosomal protein lateral stalk subunit P1, also known as RPLP1, is controlled transcriptionally by CNN3, and participates in the CNN3-mediated regulation of the viability and motility of cervical cancer cells." (PMID 32051425, 2020). "Rescue experiments further confirmed that RPLP1 restoration partially or completely reversed the proliferation, migration, and invasion inhibited by CNN3 knockdown in cervical cancer cells." (PMID 32051425, 2020). "Thus, our results, combined with those from previous studies, suggest that RPLP1, as a downstream gene of CNN3, plays a key role in regulating malignant behaviours of cervical cancer cells." (PMID 32051425, 2020). "Our results suggest that RPLP1 plays the same role in cellular viability and activity as CNN3, and may participate in CNN3-regulated malignant behaviours in cervical cancer cells." (PMID 32051425, 2020). "To explore the potential mechanism of CNN3-mediated regulation of RPLP1 expression, we examined the distribution of CNN3 in wild-type cervical cancer cells and found a trace amount of CNN3 proteins in the nucleus, which was in line with the immunofluorescence results in other studies." (PMID 32051425, 2020).
colon cancer (2 papers, 2018 to 2024). "Other research studies have reported that RPLP1 is associated with the progression of colon cancer and gynecologic tumors." (PMID 30386179, 2018). "In colon cancer, RPLP1 gene expression is significantly enhanced." (PMID 30386179, 2018). "In colon cancer, RPLP1 expression was fivefold up-regulated in cancerous versus normal tissues." (PMID 30386179, 2018).
dengue (2 papers, 2012 to 2023). "It would be then interesting to test if RPLP1 and RPLP2 knockdowns affect the luciferase activity from the dengue replicon at late time points, as observed upon GRK2 knockdown." (PMID 23029581, 2012). "Notably, studies have reported that in dengue virus infection, the silencing or the knockdown of ribosomal proteins RPL18 and RPLP1/2 significantly reduced the viral replication and translation as well as the viral yield, indicating the importance of ribosomal proteins in the virus life cycle." (PMID 37022180, 2023).
male infertility (2 papers, 2014 to 2022). The inability of the male to effect fertilization of an ovum after a specified period of unprotected intercourse. "For example, mutations in Rplp1 result in brain atrophy, male infertility, and kinked tails whereas the Rpl38 mutant mice exhibit craniofacial dysmorphia, microphthalmia, exencephaly, and homeotic transformations of the axial skeleton." (PMID 35013307, 2022). "Rplp1 heterozygosity caused body size reductions, male infertility, systemic abnormalities in various tissues and a high frequency of early postnatal death." (PMID 24959908, 2014).
triple-negative breast carcinoma (2 papers, 2018 to 2020). An invasive breast carcinoma which is negative for expression of estrogen receptor (ER), progesterone receptor (PR), and human epidermal growth factor receptor 2 (HER2). "Altogether, our findings indicate RPLP1 is a poor prognostic potential biomarker and anti-metastasis candidate therapeutic target in triple-negative breast cancer." (PMID 30386179, 2018). "RPLP1 is upregulated in triple-negative breast cancer (TNBC) tissues and cells, and high expression levels correlate with an increased risk of recurrence and metastasis." (PMID 30386179, 2018). "In addition, RPLP1 mediates cell invasion by affecting the epithelial-mesenchymal transition in triple-negative breast cancer cells." (PMID 32051425, 2020).
adenomyosis (1 paper, 2023). The growth of endometrial tissue inside the muscular wall of the uterine corpus. "In addition to playing a functional role in adenomyosis, endometrial cancer and endometriosis pathophysiology, RPLP1 may have value as a diagnostic marker." (PMID 36769010, 2023). "RPLP1 protein was up-regulated in eutopic epithelia as well as in adenomyosis lesions compared to eutopic endometria from control subjects." (PMID 36769010, 2023). "A total of 12 control endometrial biopsies and 20 eutopic endometrial and matched adenomyosis biopsies as well as 103 endometrial adenocarcinoma biopsies were evaluated for RPLP1 localization by immunohistochemistry." (PMID 36769010, 2023). "Two-dimensional (2D) in vitro studies support a functional role of RPLP1 in both cell survival and migration, both processes which are hallmarks of adenomyosis and endometrial cancer." (PMID 36769010, 2023). "Outcomes from the current study indicate that for adenomyosis, RPLP1 expression is increased in eutopic endometrial tissue, and our prior results suggest that it is also expressed in eutopic endometria from subjects with endometriosis." (PMID 36769010, 2023). "In summary, RPLP1 protein is over-expressed in adenomyosis and endometrial cancer compared to endometrial tissue from women without disease." (PMID 36769010, 2023). "Ectopic adenomyotic stromal tissue expression of RPLP1 was minimal (H-score = <50), similar to eutopic endometrial stromal from adenomyosis subjects as well as controls." (PMID 36769010, 2023). "We first examined RPLP1 expression and localization in uterine tissue from adenomyosis patients and controls using the 7-point scoring system (0, 0.5, 1.0, 1.5, 2.0, 2.5 or 3.0) defined under Section 4.2." (PMID 36769010, 2023). "Comparisons between menstrual cycle stages within tissue type revealed that in eutopic endometria from adenomyosis subjects, RPLP1 expression was significantly (p < 0.05) lower during the secretory stage of the menstrual cycle compared to the proliferative stage." (PMID 36769010, 2023). "To evaluate if a similar pattern of expression and function for RPLP1 exists in adenomyosis and endometrial cancer, we examined RPLP1 expression in adenomyosis and endometrial cancer tissue specimens and assessed its function in vitro using well-characterized cell lines." (PMID 36769010, 2023). "However, larger studies would have to be conducted to evaluate the ability of RPLP1 endometrial tissue expression to distinguish between controls and subjects who may have either endometriosis and/or adenomyosis." (PMID 36769010, 2023). "Emerging data suggest that RPLP1 is a multi-functional protein capable of modulating cell proliferation, migration, invasion and epithelial to mesenchymal transition, all of which are common characteristics of epithelial cells of adenomyosis, endometriosis and endometrial cancer." (PMID 36769010, 2023). "In our current study, regardless of patient age, RPLP1 was consistently overexpressed in adenomyosis and endometrial cancer tissue." (PMID 36769010, 2023). "With the current lack of biomarkers used for identification of adenomyosis, endometriosis and endometrial cancer, RPLP1 could prove to be a less invasive biomarker." (PMID 36769010, 2023).
appendicitis (1 paper, 2016). Acute inflammation of the vermiform appendix. "Conversely, most of the coding transcripts, such as RPLP1 and RPS26, were decreased in the blood of appendicitis patients." (PMID 27417541, 2016).
Endometrial Adenocarcinoma (1 paper, 2023). "Knockdown of RPLP1 in endometrial adenocarcinoma cell lines was associated with reduced cell survival and migration." (PMID 36769010, 2023). "We next examined RPLP1 expression in endometrial adenocarcinomas compared to control endometrial tissue." (PMID 36769010, 2023). "To begin to evaluate the functional consequence of elevated RPLP1 expression in endometrial cancer, we implemented well-characterized cell lines which represent Type I human endometrial adenocarcinomas (Ishikawa) and Type II human endometrial carcinomas (HEC-1A, HEC-1B and AN3 CA;)." (PMID 36769010, 2023). "As we previously reported that RPLP1 was essential for in vitro cell survival of the endometriotic epithelial 12Z cell line, we first determined if a similar pro-survival function existed in the endometrial adenocarcinoma cells." (PMID 36769010, 2023). "As such, it seems plausible that RPLP1 may modulate cell migration in endometrial adenocarcinoma cell lines via a similar impact on epithelial to mesenchymal transition." (PMID 36769010, 2023). "RPLP1 was also significantly up-regulated in endometrial adenocarcinoma tissue." (PMID 36769010, 2023). "Endometrial adenocarcinoma cell lines, Ishikawa, HEC1A, HEC1B and AN3 were evaluated for RPLP1 protein and transcript expression, while in vitro function was evaluated by knocking down RPLP1 expression and assessing cell survival and migration." (PMID 36769010, 2023). "RPLP1 protein was also detected in all four endometrial adenocarcinoma cell lines as well as the 12Z cell line, with AN3 CA (AN3) cells exhibiting the lowest level of protein expression despite the highest level of RPLP1 transcript expression." (PMID 36769010, 2023).
endometrial carcinoma (1 paper, 2023). A malignant tumor arising from the epithelium that lines the cavity of the uterine body. "RPLP1 expression was evaluated in a human endometrial carcinoma tissue array from patients who ranged in age from 40 to 76 years." (PMID 36769010, 2023). "RPLP1 expression is up-regulated in eutopic and ectopic adenomyotic epithelia as well as in the epithelia of endometrial cancer specimens." (PMID 36769010, 2023).
endometriosis (1 paper, 2023). The growth of functional endometrial tissue in anatomic sites outside the uterine body. "Elevated levels of RPLP1 appear to be a common phenomenon in these diseases as well as endometriosis, further supporting the notion of common pathways which may exist in all three diseases." (PMID 36769010, 2023).
Flavivirus Infections (1 paper, 2023). Infections with viruses of the genus FLAVIVIRUS, family FLAVIVIRIDAE. "It has been described that flavivirus infections induce a specific expression of the RPLP1/2 ribosomal complex, promoting the accumulation of viral proteins in the early stages of infection." (PMID 37661255, 2023).